ENSG00000272916 (novel transcript)
Gene: Protein-coding gene on chromosome 10 (73,796,514 to 73,811,651, reverse strand). Ensembl gene ENSG00000272916.
Genetic constraint (gnomAD): Missense variants: 857 observed, 1,089.7 expected, observed/expected ratio (o/e) 0.79, 90% interval 0.74 to 0.83. Synonymous variants: 366 observed, 418.14 expected, observed/expected ratio (o/e) 0.88, 90% interval 0.8 to 0.95.